KMT5C (lysine methyltransferase 5C)
Description:
Histone methyltransferase that specifically methylates monomethylated 'Lys-20' (H4K20me1) and dimethylated 'Lys-20' (H4K20me2) of histone H4 to produce respectively dimethylated 'Lys-20' (H4K20me2) and trimethylated 'Lys-20' (H4K20me3) and thus regulates transcription and maintenance of genome integrity. In vitro also methylates unmodified 'Lys-20' (H4K20me0) of histone H4 and nucleosomes. H4 'Lys-20' trimethylation represents a specific tag for epigenetic transcriptional repression. Mainly functions in pericentric heterochromatin regions, thereby playing a central role in the establishment of constitutive heterochromatin in these regions. KMT5C is targeted to histone H3 via its interaction with RB1 family proteins (RB1, RBL1 and RBL2) (By similarity). Facilitates TP53BP1 foci formation upon DNA damage and proficient non-homologous end-joining (NHEJ)-directed DNA repair by catalyzing the di- and trimethylation of 'Lys-20' of histone H4. May play a role in class switch reconbination by catalyzing the di- and trimethylation of 'Lys-20' of histone H4 (By similarity).
Synonyms: Suv4-20h2; SUV420H2; MGC2705
Tractability: Small molecule: a high-quality ligand is known; it has a high-quality binding pocket. PROTAC: ubiquitination databases record sites on it; a small molecule that binds it is known.
Target class: Writer; Protein methyltransferase; Epigenetic regulator
Chemical probes: A-196 (high quality)
Gene: Protein-coding gene on chromosome 19 (55,339,367 to 55,348,121, forward strand). Ensembl gene ENSG00000133247.
Subcellular location: Nucleus; Chromosome
Subcellular location (Human Protein Atlas): Nucleoplasm
Pathways (Reactome):
Chromatin organization: PKMTs methylate histone lysines
Gene Ontology:
Molecular function: chromatin binding; histone H4K20 methyltransferase activity; histone H4K20 monomethyltransferase activity; histone H4K20me methyltransferase activity; protein binding; S-adenosyl-L-methionine binding; histone H4 methyltransferase activity; histone binding
Biological process: DNA repair; positive regulation of double-strand break repair via nonhomologous end joining; positive regulation of isotype switching; chromatin remodeling
Cellular component: heterochromatin; nucleoplasm; pericentric heterochromatin; nucleus; chromosome; condensed chromosome, centromeric region
Genetic constraint (gnomAD): Loss-of-function variants: 20 observed, 34.11 expected, observed/expected ratio (o/e) 0.59, 90% interval 0.41 to 0.85. The synonymous counts are far from expectation, so gnomAD's model fits this gene poorly and the ratio says little. Missense variants: 519 observed, 539.28 expected, observed/expected ratio (o/e) 0.96, 90% interval 0.89 to 1.03. Synonymous variants: 265 observed, 214.94 expected, observed/expected ratio (o/e) 1.23, 90% interval 1.11 to 1.37.
Homologues: Orthologues: chimpanzee KMT5C (99% identical), macaque KMT5C (97% identical), dog KMT5C (88% identical), pig KMT5C (87% identical), guinea pig KMT5C (83% identical), rat Kmt5c (82% identical), mouse Kmt5c (81% identical), tropical clawed frog kmt5c (56% identical), zebrafish kmt5c (38% identical). Paralogues in human: KMT5B (44% identical).
Diseases named in the same sentence as KMT5C in open-access papers:
KMT5C is named in the same sentence as 12 diseases in open-access papers, as found by Europe PMC text mining. Sharing a sentence is not in itself a finding about the gene and the disease. The quoted sentences say what the papers report.
breast carcinoma (5 papers, 2014 to 2025). "In this body of work miR-29a was shown to directly target the KMT5C transcript leading to epithelial to mesenchymal transition (EMT), promoting migration and invasion of breast cancer cells, further supporting a tumor suppressive role for KMT5C." (PMID 37671044, 2023).
endometrial carcinoma (1 paper, 2023). A malignant tumor arising from the epithelium that lines the cavity of the uterine body. "Although CHTF18 and KMT5C have not been shown to correlate with RCC, they played a role in the development of other tumors; abnormalities in CHTF18 promoted endometrial carcinoma, and KMT5C played a role in non-small cell lung cancer." (PMID 36816355, 2023).
cancer (8 papers, 2010 to 2025). A tumor composed of atypical neoplastic, often pleomorphic cells that invade other tissues. "This work first observes that upregulation of KMT5C in NSCLC correlated with cancer progression and poor patient prognosis." (PMID 40126333, 2025). "In this study, we find that upregulation of KMT5C in NSCLC correlates with cancer progression and poor patient prognosis." (PMID 40126333, 2025). "Although previously studies have reported that KMT5C plays an important role in cancer development, the relationship between KMT5C and immunity regulation remains unclear." (PMID 40126333, 2025).
tumor (8 papers, 2015 to 2025). "To further examine the role of KMT5C in vivo, we generated a tumor xenograft model using A549 cells with control or KMT5C knockdown." (PMID 40126333, 2025). "Next, we further assessed the role of KMT5C in tumor metastasis using a transwell assay, and found that KMT5C overexpression indeed significantly enhanced the migration and invasion ability of A549 and HCC827 cells." (PMID 40126333, 2025). "Taken together, these findings indicate that KMT5C exerts pro‐tumor cell growth and metastasis in NSCLC." (PMID 40126333, 2025). "The current work is the first to reveal the regulatory effect of KMT5C in the tumor immunity microenvironment." (PMID 40126333, 2025). "Consistently, the Kmt5c knockdown group had the lower tumor volume and weight than the control group." (PMID 40126333, 2025). "Next, we further determined the expression of KMT5C in our in‐house NSCLC cohort using IHC staining, the expression level of KMT5C was observed to be upregulated in tumor tissues compared with that in peritumor tissues, and was also increased in advanced tumor stages." (PMID 40126333, 2025). "Conversely, knockdown the expression of KMT5C could remarkably reduce the tumor cell numbers of migration and invasion." (PMID 40126333, 2025). "We further demonstrate the pro‐tumor role of KMT5C in NSCLC progression in vitro and in vivo." (PMID 40126333, 2025). "Given that KMT5C knockdown can improve the immunosuppressive tumor microenvironment, we wondered whether KMT5C inhibition could potentiate the response of NSCLC to immunotherapy." (PMID 40126333, 2025). "Similarly, the protein level of KMT5C was also upregulated in the tumor tissues relative to its adjacent counterparts." (PMID 40126333, 2025). "To further examine the role of KMT5C in tumor metastasis in vivo, we generated a mouse lung metastasis model by tail vein injection of the LLC cells with control or Kmt5c knockdown." (PMID 40126333, 2025).
KMT5C also shares sentences with these, for which no sentence is quoted: lung carcinoma (2 papers); bladder cancer (1); clear cell renal cell carcinoma (1); colon cancer (1); liver cancer (1); non-small cell lung carcinoma (1); Obesity (1); pancreatic cancer (1).